CDK6 (cyclin dependent kinase 6)
Diseases named in the same sentence as CDK6 in open-access papers (continued):
Sharing a sentence is not in itself a finding about the gene and the disease.
colon carcinoma (45 papers, 2008 to 2025). "It has been reported that c-Myc induced cell proliferation is generally associate with an increase in CDK4 and CDK6 activities, which regulated G1 progression in colon cancer cells." (PMID 34659577, 2021). "Immune cell expression analysis indicated that CDK6 expression level and risk positively correlated with M2 macrophages, which promote tumor development, progression, and poor outcome (e.g., in colon cancer)." (PMID 35896848, 2022). "In conclusion, our study demonstrated that AGA extract has potential to inhibit the proliferation, metastasis by inducing apoptosis and G1 phase arrest efficiency by inhibiting the CDK2, CDK6/CDK4 proteins in colon cancer cells." (PMID 36597025, 2023). "In this respect, it is worth noting that GPR15L has been recently reported to interact with SUSD2 to inhibit colon cancer cell growth via G1 arrest, which is induced by down-regulating cyclin D1 and cyclin-dependent kinase 6 (CDK6)." (PMID 38074634, 2023). "On the other hand, the depletion of uS7 promoted the degradation of the CDK6 protein in both human colon cancer cell lines, and we observed a direct interaction between uS7 and CDK6." (PMID 35681048, 2022). "In colon cancer cells, hsa_circ_000984 competitively combined with miR-106b as a ceRNA and increased CDK6 expression effectively." (PMID 36313671, 2022). "The knockdown of uS7 induces G1 cell cycle arrest with the downregulation of CDK6 in colon cancer cells." (PMID 35681048, 2022). "The circRNA hsa_circ_000984 was also found to promote colon cancer growth and metastasis by binding miR-106b to increase CDK6 expression." (PMID 32908453, 2020). "The levels of lncRNA MYU, a downstream target of c-Myc, are increased in most colon cancers and enhance the G1-S transition in the cell cycle process via its interaction with hnRNP-K and subsequent stabilization of CDK6 in colon cancer cells." (PMID 33246471, 2020). "NEAT1 was also shown to promote colon cancer progression via up-regulating CDK6 by sponging miR-495-3p." (PMID 33336058, 2020). "CBX3 can promote the formation of colon cancer by inhibiting the expression of CDK6/p21, which are cell cycle (G1 phase to S phase) related genes." (PMID 31138312, 2019). "We have identified a novel role for CDK6 as a transcriptional regulator to link cell-cycle progression in colon cancer." (PMID 28193906, 2017). "To investigate the specific biological role of CDK6 in colon cancer, we knocked down CDK6 expression in HCT116 and HCT116-B3 cells." (PMID 28193906, 2017). "The deletion of CBX3 in colon cancer cells curb cell cycle progression (G1 phase to S phase) suppress cell proliferation in vitro and tumor growth in vivo, where CDK6 and p21 are consistently upregulated." (PMID 28193906, 2017). "In murine models of colon cancer, miR-143 and miR-145 played tumor suppressive functions by targeting Cdk6, CCND2 and E2F3." (PMID 28947999, 2017). "We had identified that the deletion of CBX3 increases CDK6 and p21 expression in colon cancer cells." (PMID 28193906, 2017). "Our results have shown that c-Myc can lead to reaccumulation of cyclinD1, CDK4 and CDK6 in hypoxia, and this potentially explain the G1/S switch induced by c-Myc in colon cancer cells in a low-oxygen environment." (PMID 27793037, 2016). "A recent study reported that low DLC1 by itself did not have prognosis value in colon cancer patients, but there is a prognostic significance when low DLC1 was combined with low p15 or high Cdk6 in colon cancer patients." (PMID 26223867, 2015). "For example, poor prognosis was reported to be associated with low DLC1, low CDKN2A/B and high CDK4 in lung cancer, and low DLC1, low CDKN2B, and high CDK6 in colon cancer." (PMID 25425654, 2014). "Studies of lung and colon cancer show that underexpression of DLC1 frequently co-occurs with deregulated expression of cell cycle genes such as CDK6, CDK4, CDKN2A, and CDKN2B." (PMID 25425654, 2014).
colon carcinoma (continued). "Low DLC1 expression is found to frequently co-occur with aberrant expression of cell cycle genes including CDK6 in human lung and colon cancer." (PMID 25425654, 2014). "In line with this study, a previous study has shown that miR-145 inhibits Cdk6 expression by direct targeting its 3’-UTR in colon cancer cells." (PMID 23710609, 2013). "CDK6 is an established target of miR-124 in HCT-116 colon cancer cells, a predicted target of miR-137 (TargetScan and PicTar), and has been functionally implicated in the development of multiple malignancies." (PMID 18577219, 2008). "Transfection of human colon carcinoma cells with an miR-1-3p mimic directly targeting CDK6 could increase apoptosis and cell cycle arrest in colon carcinomas." (PMID 39457531, 2024). "Finally, hnRNPK interacts with the MYU lncRNA, a c-Myc target that is overexpressed in colon cancer, to increase CDK6 transcription, as well as to promote the G1-S cell cycle transition during colon cancer, both of which are driven by Wnt/c-Myc signaling." (PMID 31110205, 2019). "Therefore, we identify a new mechanism by which CBX3 promotes colon cancer progression via the CDK6/p21 pathway during cell cycle." (PMID 28193906, 2017). "We had previously found that CBX3 can inhibit the expression of CDK6 and P21 in colon cancer." (PMID 28193906, 2017). "We focused on E2F3 because CDK6 has been reported as a target of miR-145 in colon cancer." (PMID 25762621, 2015). "Western blot analysis of CB42 and several human colon tumor xenograft lines confirmed high expression of CDK6 in CB42 and SW620 and detectable CDK6 in HCT116 and HCC2998 indicating that activation of CDK6 may be advantageous for human tumor xenografts." (PMID 25162504, 2014). "Finally, miR-124 overexpression in HCT-116 colon cancer cells inhibits the expression of CDK6, an established target of miR-124." (PMID 18577219, 2008). "Similarly, CDK4/6 inhibition has been shown to inhibit the proliferation of several colon cancer cell lines in vitro, induce regression of a human colon cancer xenograft (Colo-205), and induce regression of multiple myeloma xenografts which specifically overexpress CDK6." (PMID 25162504, 2014). "This study revealed that remimazolam promoted the cell-cycle progression and proliferation of HCT8 colon cancer cells by upregulating CDK1, PTTG1, CDC25C, CDK4, PLK1, PCNA, Ki67, RNASEH2B, FEN1, Cyclin D1,CD44 CDK2, CDKN3, CDC45, IQGAP3, and CDK6." (PMID 38725628, 2024). "We evaluated the association of hnRNPA2B1 with BCL2L1, BCL2, MDM2, cMYC, CD44, CDK6, cJUN, and TXNP in HCT116 colon cancer cells treated with 70 μg/ml of the crude extract." (PMID 33163396, 2020). "We found high abundances of CDK6 accompanied by reduced or undetectable expression of p21, where CBX3 expression was significantly upregulated in colon cancer tissue." (PMID 28193906, 2017). "On the other hand, it has been shown that DNA hypermethylation in the promoters of miR-124a and miR-127 leads to their transcriptional silencing in colon cancer models and influences the expression of two oncogenes, such as BCL6 and CDK6." (PMID 22277129, 2012). "Taken together, these results suggest that GSPT1 regulates CyclinD1, CDK4, and Cdk6 through GSK-3 β, and indirectly affects the expression of cyclinE and CDK2 through p21 and p27, thus regulating the transformation of colon cancer cells from the G1 phase to S phase and promoting tumor progression." (PMID 33819920, 2021). "Besides driving the transcription of tumor-promoting genes such as c-Myc and cyclin-dependent kinase-6 (CDK6), a previous study explored a critical oncogenic role of NFATc2 in colitis-induced colon cancer by control of proinflammatory cytokine IL-6 production." (PMID 32041943, 2020).
colon carcinoma (continued). "Treatment of HCT116 colon cancer cells with 70 μg/ml of C. orbiculata extract resulted in an increase in the co-precipitation of hnRNPA2B1 with BCL2L1, BCL2, MDM2, cMYC, CD44, CDK6, and cJUN mRNA." (PMID 33163396, 2020). "Other findings indicated that EGFR signals could coordinately control multiple G1 regulators via miR-143 and its target K-ras and miR-145 and its targets MYC, cdk6, CCND2 or E2F3, which play a role in cell cycle progression in colon cancer." (PMID 28947999, 2017). "Taken together, our data indicates that CDK6 knocked down promotes colon cancer cell proliferation in the absence of CBX3." (PMID 28193906, 2017). "Thus, data from human colon tumors and cell lines indicate that the CDK6 pathway is activated and/or overexpressed without direct amplification of the gene." (PMID 25162504, 2014). "To further confirm that CBX3 promotes colon cancer progression via regulating the expression of CDK6/p21, we examined the expression of CBX3, CDK6 and p21 in human non-cancerous tissue (NCA) and cancerous tissue (CA)." (PMID 28193906, 2017). "To see whether enhanced anti-tumor immunity in vivo is related to the absence of CDK6 in T cells, we subcutaneously injected Cdk6fl/fl CD4-Cre and Cdk6fl/fl mice with the colon carcinoma cell line MC38, which is surveilled by CD8+ T cells." (PMID 34248938, 2021). "One propagated tumor line, CBP1, from a model ES cell line overexpressing CDK14 in addition to β-Catenin was tested to assess whether a propagatable colon tumor lacking KRAS activation and CDK6 amplification would respond to either of the targeted agents or their combination." (PMID 25162504, 2014).
ovarian carcinoma (44 papers, 2015 to 2025). A malignant neoplasm originating from the surface ovarian epithelium. "Dysregulation of CDK6 is common in cancers and has been previously been implicated in dysfunctional proliferation and disease progression in ovarian carcinomas." (PMID 37621654, 2023). "Many evidences suggest that CDK6 regulates the sensitivity to platinum in ovarian cancer cells and that its high expression is associated with a platinum-resistant phenotype." (PMID 34204543, 2021). "Since CDK6 is a potential resistance marker of MEKi, as well as a single therapeutic target for ovarian cancer patients, we selected palbociclib as the specific inhibitor of CDK4/6 to use in combination with MEKi." (PMID 40568132, 2025). "Studies have indicated that SNHG17 is upregulated in ovarian cancer and acts as a molecular sponge for miR-214-3p, relieving miR-214-3p’s inhibitory effect on the cell cycle regulator CDK6, thereby promoting the growth of ovarian cancer cells." (PMID 38439898, 2024). "In a pre-clinical study, gene silencing of or the pharmacological inhibition of CDK6 increased the platinum sensitivity in ovarian cancer cell lines." (PMID 38612869, 2024). "In ovarian cancer cells, platinum treatment can phosphorylate CDK6, which has been shown to stabilise the FOXO3 transcription factor, resulting in the upregulation of ATR, a key DNA repair factor involved in platinum resistance." (PMID 38612869, 2024). "Circ_0072995 accelerated the tumor progression via regulating miR-147a and CDK6 expression in epithelial ovarian cancer." (PMID 38152652, 2023). "In conclusion, circ_0000714 targeted miR-370-3p/RAB17 axis and activated CDK6/RB signaling pathway, leading to reduction of paclitaxel resistance in ovarian cancer." (PMID 38152652, 2023). "For instance, miR-147a represses the growth and metastasis of NSCLC via targeting IFITM1 and the progression of epithelial ovarian cancer through the down-regulation of CDK6 protein." (PMID 35196205, 2022). "After 48 h of bexarotene treatment, the levels of CDK4, CDK6, Cyclin D1, and phospho-RB decreased in both ovarian cancer cell lines." (PMID 35778597, 2022). "In ovarian cancer, exosomal transfer of miR-433 can promote paclitaxel resistance through the induction of cell senescence related genes including cyclin-dependent kinase 6 (CDK6), MAPK14, E2F3, and CDKN2A." (PMID 36117723, 2022). "We and others have evaluated the expression of both CDK4 and CDK6 in epithelial ovarian cancers with interesting results." (PMID 34204543, 2021). "Here, we describe the possible biological role of CDK4 and CDK6 complexes in ovarian cancer and provide the rationale for the use of CDK4/6 inhibitors in this pathology, alone or in combination with other drugs." (PMID 34204543, 2021). "Here, we review the role of CDK4 and CDK6 complexes in ovarian cancer and propose the possible use of their inhibitors in the treatment of ovarian cancer patients with different types and stages of disease." (PMID 34204543, 2021). "Taken together, our results showed that SNHG15 promoted ovarian cancer cell proliferation through upregulated CDK6 via inhibiting mir-370-3p." (PMID 34734088, 2021). "It has been demonstrated that miR-211 is downregulated in ovarian cancer, and restoration of miR-211 inhibits cell proliferation by suppressing cyclin D1 and CDK6 expression." (PMID 31235732, 2019). "Among nine of the 11 multidrug-resistant ovarian cancer cell line variants, the drug-resistant gene MDR1 (ABCB1) is co-expressed with multiple genes located in 7q21, including CROT and CDK6." (PMID 31295943, 2019). "The exosome miR-21 promotes ovarian cancer progression by regulating CDK6." (PMID 39057685, 2024). "Genomic alterations in CDK4 and CDK6 have been reported in ovarian cancer." (PMID 38612869, 2024).
ovarian carcinoma (continued). "Similarly, reduction of levels of the ribosomal protein RPS6 in ovarian cancer cells caused downregulation of CDK2, CDK4, CDK6, cyclin E, and cyclin D1, thereby blocking the transition from G0/G1 to S phase and suppressing cell proliferation." (PMID 38802745, 2024). "Similarly, a recent study has indicated that miR-370-3p restrains the progression of ovarian cancer by reducing CDK6 expression." (PMID 36755807, 2023). "In conclusion, our study suggests that SNHG15 may be used as a prognostic indicator in ovarian cancer and reveals the SNHG15/miR-370-3p/CDK6 pathway in ovarian cancer." (PMID 34734088, 2021). "Here, we will focus on the possible roles that the inhibition of two central regulators of cell cycle progression, namely CDK4 and CDK6, may play in the context of ovarian cancer." (PMID 34204543, 2021). "To demonstrate whether SHNG15 regulated CDK6 in ovarian cancer, we analyzed the CDK6 expression after SNHG15 knockdown, and in the si-SNHG15 group, CDK6 was lower than that in the si-NC group, indicating that SNHG15 regulated CDK6 expression in ovarian cancer." (PMID 34734088, 2021). "CDK6 regulated cell cycle progression under physiological and pathological conditions, and published evidences have showed that CDK6 was important in the development of ovarian cancer." (PMID 34734088, 2021). "Similarly, CDK6 expression protects epithelial ovarian cancer cells from platinum-induced cell death controlling ATR transcription through FOXO3a phosphorylation and stabilization, directly impacting on DDR during the S phase of the cell cycle." (PMID 34204543, 2021). "In particular, cells can become sensitized to cisplatin after ATR depletion; a recent report shows that CDK6 regulates transcription of ATR, and that CDK6 inhibition therefore sensitizes epithelial ovarian cancer cells to death from cisplatin due to an impaired DNA damage response." (PMID 29644000, 2018). "In our study, mutational analysis of TCGA ovarian cancer data has shown that a significant percentage of patients have mutations or dysregulated expression of CDKN2A, CDK4, CDK6, or CCND1 that would likely make them good candidates for CDK4/6 inhibitor therapy." (PMID 29644000, 2018). "Everolimus decreased expression of CDK6 and cyclin D1 and increased expression of p21 in both cell lines after 24 hours of treatment, suggesting that everolimus induces growth inhibition through induction of G1 phase arrest in ovarian cancer cells." (PMID 26959121, 2016). "Cyclin-dependent kinases (CDK2, CDK4, CDK6), cyclin D1, cyclin E1 and phosphorylated retinoblastoma (pRB1) are key regulators of the G1/S cell cycle checkpoint and may influence platinum response in ovarian cancers." (PMID 38612869, 2024). "In this study, RPS6 knockdown resulted in decreased Cyclin E, CDK2, Cyclin D1, CDK4, and CDK6 levels, and reduced Rb phosphorylation, thus hindering the transition from G0G1 to S phase, causing most cells to be blocked in G0G1 phase, thereby inhibiting ovarian cancer cell growth." (PMID 32862831, 2020). "Additionally, miR-145 could sensitize ovarian cancer cells to paclitaxel by directly targeting CDK6 to reduce the expression of CDK6, along with downregulation of P-gp." (PMID 31582906, 2019). "Mir-214-3p has a suppressive effect on CDK6 and on MAPK1, and its downregulation promotes cell-cycle progression, proliferation, migration, and invasion of ovarian cancer cells." (PMID 37569592, 2023). "In general, it was observed that CDK6, more than CDK4, was expressed at high levels in epithelial ovarian cancer." (PMID 34204543, 2021). "Consistently, the G0/G1 checkpoint regulators, such as cyclin D1, cyclin E, CDK2, CDK4, CDK6, and p-RB, are diminished by RPS6-KD in ovarian cancer cells." (PMID 35008473, 2021). "The results showed that SNHG15 was upregulated and predicted poor prognosis in ovarian cancer; in addition, SNHG15 promoted cancer cell proliferation through upregulated CDK6 via inhibited mir-370-3p." (PMID 34734088, 2021).
ovarian carcinoma (continued). "The levels of p-RB, cyclin D1, cyclin E, CDK2, CDK4, or CDK6 by RPS6-KD were reduced in NSCLC cells, ovarian cancer cells, and drug-resistant melanoma cells." (PMID 35008473, 2021). "To address this hypothesis, we have comprehensively evaluated the clinicopathological significance of the CDK2, CDK4, CDK6, cyclin D1, cyclin E1, RB1 and pRB1(Ser 795) protein expression in a clinical cohort of epithelial ovarian cancer." (PMID 38612869, 2024). "Moreover, the evaluation of the miR-124 overexpression in MSC exosomes has shown the proliferation inhibition of ovarian cancer cells by arrest induction in the S phase through the downregulation of Cyclin-Dependent Kinase 2 (CDK2), CDK4, and CDK6." (PMID 34307654, 2021). "Regulation of gene transcription by CDK4 and CDK6 has a well-established role in the regulation of senescence, through the phosphorylation of the transcription factor FOXM1 and described as an important event in melanoma and ovarian cancer." (PMID 34204543, 2021). "Furthermore, with the exploration of the BORA silencing transcriptional landscape, we identified downstream effectors such as CDK6 and BCL2 whose inhibition can be used as targeted therapies for ovarian cancer management." (PMID 32268485, 2020).